MIR7-3 (microRNA 7-3)
Synonyms: hsa-mir-7-3; MIRN7-3; mir-7-3
Gene: MicroRNA gene on chromosome 19 (4,770,670 to 4,770,779, forward strand). Ensembl gene ENSG00000207630.
Gene Ontology:
Biological process: miRNA-mediated post-transcriptional gene silencing
Cellular component: RISC complex
Homologues: Orthologues: chimpanzee ptr-mir-7-3 (100% identical), macaque mml-mir-7-3 (88% identical), dog MIR7-3 (72% identical), rat Mir9 (72% identical), guinea pig MIR7-3 (71% identical), zebrafish mir7a-3 (55% identical), tropical clawed frog xtr-mir-7-3 (47% identical), Drosophila melanogaster mir-7 (46% identical). Paralogues in human: MIR7-1 (65% identical).